VCAM1 (vascular cell adhesion molecule 1)
Diseases named in the same sentence as VCAM1 in open-access papers (continued):
Sharing a sentence is not in itself a finding about the gene and the disease.
lymph node metastasis (6 papers, 2015 to 2024). "Higher VCAM-1 levels were independently associated with increased risk of lymph-node-metastasis (LNM), ≥pT3 disease, and non-organ-confined disease (NOCD (p < 0.001 for each)." (PMID 35347517, 2022). "Moreover, the univariate and multivariate analysis demonstrated that the TNM stage, lymph node metastasis, VCAM-1 expression, and CCL18 expression were independent prognostic factors." (PMID 29670110, 2018). "Statistical analysis confirmed that CCL18 overexpression was only correlated with the TNM stage, whereas VCAM-1 overexpression was correlated with the TNM stage, lymph node metastasis, and perineural invasion." (PMID 29670110, 2018). "SPARC, VCAM1 and ANGPTL4 were found positively correlated with the potentials of lung metastasis, while ITGA1 had a positive relation to lymph node metastasis of enterocoelia." (PMID 26459277, 2015). "Indeed, the protein levels of SPARC, ANGPTL4 and VCAM1 were remarkably correlated with the potentials of lung metastasis, while ITGA1 was positively related to celiac lymph node metastasis (p < 0.01)." (PMID 26459277, 2015).
lymphopenia (6 papers, 2020 to 2024). Reduction in the number of lymphocytes. "Disease severity was associated with changes in innate monocytes and neutrophils, lymphopenia, disrupted cytokine production (increased IL-8 and IP-10/CXCL10 but reduced IFNλ2/3 and IFNγ), and increased endothelial injury (myoglobin, VCAM-1)." (PMID 37598150, 2023). "In our cohort, soluble EC activation biomarkers (e.g. ICAM-1, VCAM-1, E-selectin, Ang-2, CD40L, vWF-A2) and the EC damage product, Syndecan-1, are positively correlated with thrombocytopenia, lymphopenia, anaemia, and neutrophil enrichment in the peripheral blood." (PMID 34585667, 2021).
non-small cell lung carcinoma (6 papers, 2016 to 2023). A group of at least three distinct histological types of lung cancer, including non-small cell squamous cell carcinoma, adenocarcinoma, and large cell carcinoma. "Interestingly, C-X-C chemokine receptor type 4 (CXCR4), a receptor widely reported to regulate extramedullary myeloma, was found to induce VCAM1 secretion in non-small cell lung cancer via the regulation of the metalloproteinase, ADAM17." (PMID 37568580, 2023). "JWH-105 inhibited EMT in non-small cell lung cancer cells (NSCLC) by suppressing ERK and STAT-3 activation and EGFR signaling; in addition, JWH-105 reduced invasiveness of A549 cells when co-cultured with M2 macrophages, by downregulating the expression of FAK, VCAM1, and MMP-2." (PMID 33922795, 2021).
peripheral arterial disease (6 papers, 2019 to 2024). A disorder of the arteries supplying the upper and lower extremity and the visceral organs. "In another study, VCAM-1 was identified as a marker for peripheral artery disease." (PMID 37566005, 2023). "In support of this theory, it was shown that the circulating levels of cytokines (IL-6 and TNFα), adhesion molecules (VCAM-1 and ICAM-1), and selectins in patients with peripheral arterial disease are elevated." (PMID 34447794, 2021).
pneumonia (6 papers, 2022 to 2023). An acute, acute and chronic, or chronic inflammation focally or diffusely affecting the lung parenchyma, caused by an infection in one or both of the lungs (by bacteria, viruses, fungi, or mycoplasma.). "The main enriched items for VCAM1 were recurrent pneumonia, meningitis, and basal cell carcinoma." (PMID 37760894, 2023).
renal carcinoma (6 papers, 2009 to 2024). A carcinoma arising from the epithelium of the renal parenchyma or the renal pelvis. "In VCAM1, a variant haplotype centered on rs3917010 was also associated with an increased risk of renal cancer (CAT OR: 1.25, 95% CI: 1.01–1.54)." (PMID 19603096, 2009). "Furthermore, VCAM-1 over-expression in renal carcinoma is associated with tumor stage, tumor grade, overall survival and subtype of renal carcinoma (RCC) tumors." (PMID 24583847, 2014). "In 2022, a novel specific cell surface expression pattern in RCC represented by the NCI-60 tumor cell panel was identified and confirmed that VCAM1 is a promising novel immunotherapeutic target for the treatment of renal cancer particularly." (PMID 37622107, 2023). "Further data mining revealed that CD106 (VCAM1) in particular is a promising novel immunotherapeutic target for the treatment of renal cancer." (PMID 36221114, 2022). "Currently, the role of VCAM1 in renal cancer is less explored, with data pointing towards protective roles in this cancer entity, as well as a potential involvement of VCAM1 in tumor immune evasion." (PMID 36221114, 2022). "In addition, with a haplotype-based sliding window method, we identified the same genes with regions that were associated with renal cancer risk at a FDR level <10%: CASP1/5/4/12, EGFR, IGFBP3, and VCAM1." (PMID 19603096, 2009). "Likewise, CD106 (VCAM1) might be an interesting and potential novel cell surface biomarker as well as an attractive target for immunotherapy in the context of renal cancer." (PMID 36221114, 2022). "However, none of the VCAM1 SNPs were significantly associated with renal cancer risk after FDR adjustment." (PMID 19603096, 2009). "Especially CD106 (VCAM1) and EGFR seem promising immunotherapeutic targets that show higher surface expression levels in the context of renal cancer." (PMID 36221114, 2022). "This set of data provides further independent indications that VCAM1, EGFR and CD24 are highly expressed in renal cancers and that their high expression is a poor prognostic marker for survival." (PMID 36221114, 2022).
uveitis (6 papers, 2021 to 2025). An inflammatory process affecting a part of or the entire uvea. "The ICAM-1/LFA-1 and VCAM-1/VLA-4 are the main pathways reportedly involved in uveitis development in the literature." (PMID 35008929, 2022). "DEG analysis unravel that cytokines, chemokines, and adhesion molecules, including ICAM-1 and VCAM-1, were highly expressed in RVECs in uveitis." (PMID 35401507, 2022). "There is direct evidence of VCAM-1 as well as ICAM-1/LFA involvement in uveitis development, as an increased expression was detected in iris biopsies from patients relative to controls." (PMID 35008929, 2022). "This study identified six significantly upregulated genes (CDKN1A, VCAM1, NFKBIA, ICAM1, IRF1, and CXCL10) and demonstrated that QHRGF exerts therapeutic effects on uveitis using in vivo experiments." (PMID 40718791, 2025). "There is evidence of increasing expression of ICAM-1 and VCAM-1 in studies of human uveitis retinal specimens and from EAU retinal tissues and enhanced VCAM-1 expression specifically in focal areas of the retinal post-capillary venules when inflammation is initiated and when EAU is evident." (PMID 33602234, 2021).
allergic asthma (5 papers, 2005 to 2022). A asthma with a basis in a pathological type I hypersensitivity reaction. "Transendothelial migration of eosinophils to the airways of patients with allergic asthma is stimulated by IL-4 via induction of vascular cell adhesion molecule-1 (VCAM-1), which specifically interacts with its eosinophil counterligand very late antigen-4 (VLA-4)." (PMID 25878402, 2015).
Arterial thrombosis (5 papers, 2020 to 2024). The formation of a blood clot inside an artery. "EC autophagy deficiency improves the levels of vascular cell adhesion molecule-1 (VCAM-1), intercellular adhesion molecule-1 (ICAM-1), von Willebrand factor, and P-selectin, thus promoting the infiltration of macrophages and foam cells, as well as increasing the risk of arterial thrombosis." (PMID 35096837, 2021).
autoimmune myocarditis (5 papers, 2016 to 2025). Autoimmune myocarditis is an autoimmune disease that affects the heart. "However, circulating VCAM1 can be affected by comorbidities, such as immunological diseases, cancer, and autoimmune myocarditis." (PMID 34593936, 2021). "Therefore, we investigated whether plasma levels of soluble VCAM-1 (sVCAM-1) directly correlated with disease activity and progression of cardiac dysfunction in the mouse model of experimental autoimmune myocarditis (EAM)." (PMID 27501319, 2016). "Similarly, vascular cell adhesion molecule-1 (VCAM-1) expression is increased in autoimmune myocarditis, though not directly correlated with disease severity." (PMID 41154703, 2025).
brain edema (5 papers, 2019 to 2025). Increased intracellular or extracellular fluid in brain tissue. "Nevertheless, the mechanisms through which CAPE ameliorates cerebral edema from a peripheral perspective may involve more than the regulation of VCAM-1 and ICAM-1." (PMID 41567629, 2025).
brain injury (5 papers, 2011 to 2024). Acute and chronic (see also brain INJURIES, CHRONIC) injuries to the brain, including the cerebral hemispheres, CEREBELLUM, and brain STEM. "The relevance of this major discrepancy between the two ICH models on leukocyte invasion, neuroinflammation and outcome needs to be further investigated because of the key role of VCAM-1 in the inflammatory cascade after brain injury." (PMID 21967730, 2011). "Consequently, VCAM-1 liposomes represent a promising platform for the targeted delivery of therapeutics to the brain following traumatic brain injury." (PMID 38857220, 2024). "Furthermore, we have established the therapeutic efficacy of VCAM‐1‐targeting, miR‐143‐3p inhibitor‐encapsulated EVs in promoting functional recovery following acute brain injuries." (PMID 38044319, 2024). "Not much is known about the contribution of human VCAM-1 to neuroinflammation, though its levels increased acutely in the blood and CSF after brain injuries." (PMID 27737716, 2016).
cervical carcinoma (5 papers, 2021 to 2025). A carcinoma arising from either the exocervical squamous epithelium or the endocervical glandular epithelium. "Six interesting core DEPs (SPARC, HPX, VCAM1, TFRC, ERN1 and APMAP) were confirmed to be potential plasma diagnostic markers for LVSI and LNM in cervical cancer patients." (PMID 37689639, 2023).
coagulopathy (5 papers, 2011 to 2025). "These seven markers were: Pentraxin-3 (‘disturbed vasculogenesis’), VCAM-1 and ICAM-1 (both EC Activation), Thrombomodulin (‘coagulopathy’), MCP-1, IP-10 and VEGF (all ‘disturbed angiogenesis’)." (PMID 37194071, 2023). "Third, we only determined serum thrombomodulin levels and we did not analyze other biomarkers of coagulopathy or vascular injury such as protein C, protein S, ICAM-1, VCAM-1 and E-selectin." (PMID 28771554, 2017).
influenza infection (5 papers, 2017 to 2022). "Intravital staining of lung vessels following influenza infection suggested a unique compartmentalization of VCAM-1 and ICAM-1, respectively, between virus infected peribronchial vessels and lung capillaries." (PMID 36895258, 2022). "In accordance with these data, the present study demonstrated an increase in serum level of VCAM-1, which rose from a baseline level of 493.7 ± 44.34 ng/ml to 542.3 ± 49.60 ng/ml post-influenza immunisation, in participants untreated with anti-platelet agents (Group 4; p=0.0022 vs baseline)." (PMID 29156815, 2017). "Interestingly, VCAM-1 transcripts in the lungs of mice are upregulated from 2 to 8 days after influenza infection." (PMID 28382037, 2017). "Since we previously showed that MCp were recruited to the lung in a VCAM-1-dependent fashion in a mouse model of allergic airway inflammation, the induced VCAM-1 expression suggests that MCp use the same transmigration mechanism in influenza infection and allergic airway inflammation." (PMID 28382037, 2017). "This indicates that MCp may be recruited in a VCAM-1-dependent manner upon influenza infection." (PMID 28382037, 2017). "Furthermore, influenza infection augmented the expression of intercellular adhesion molecule 1 (ICAM1), vascular cell adhesion molecule 1 (VCAM-1) and E-selectin on human aortic endothelial cells (HAECs) and human umbilical vein endothelial cells (HUVECs)." (PMID 34359859, 2021). "Notably, while alveolar capillaries in influenza-infected lungs lacked VCAM-1 expression, high surface ICAM-1 expression was detected on all capillaries." (PMID 36895258, 2022).
liver cirrhosis (5 papers, 2010 to 2024). "The aim of this study was to explore and correlate the behavior of sVAP-1 with that of the soluble vascular cell adhesion molecule-1 (sVCAM-1) and intercellular adhesion molecule-1 (sICAM-1) and with the severity of liver cirrhosis." (PMID 39000418, 2024). "Liver cirrhosis tissues were probed with alpha-smooth muscle actin or VCAM-1." (PMID 20416094, 2010).
metastatic cancer (5 papers, 2020 to 2023). A carcinoma which has spread from the original site of growth to another anatomic site. "A more detailed understanding of the dynamic involvement of Vcam1 in the complex metastasis cascade is needed before we can adequately assess its therapeutic value in metastatic cancer." (PMID 36828890, 2023). "Moreover, interactions of VCAM-1 with stroma are key factors for survival of metastatic cancer cells." (PMID 34760697, 2021).
Myocardial fibrosis (5 papers, 2014 to 2025). "MCC950 also reduced the levels of IL-1β, IL-18, vascular cell adhesion molecule 1 (VCAM-1), and intercellular adhesion molecule 1 (ICAM-1), alleviating myocardial fibrosis and infiltration of inflammatory cells." (PMID 40565074, 2025). "Indeed, macrophage recruitment which is mediated in part by Mcp-1 and adhesion molecules such as intracellular adhesion molecule 1 (ICAM-1) and vascular cell adhesion molecule 1 (VCAM-1), exerts a crucial role in myocardial fibrosis and diastolic dysfunction." (PMID 24558494, 2014). "Excessive ROS generation upregulates the expression levels of vascular adhesion molecules, particularly VCAM-1 and ICAM-1, facilitating myocardial infiltration by activated leukocytes, transformation of fibroblast into myofibroblasts, and the progression of myocardial fibrosis." (PMID 40429987, 2025).
myocardial ischemia (5 papers, 2012 to 2024). A disorder of cardiac function caused by insufficient blood flow to the muscle tissue of the heart. "PLGA-based nanosystem was furthermore used to develop reactive oxygen species (ROS)-sensitive complexes for co-delivery of siRNA against vascular cell adhesion molecule-1 (VCAM-1) and dexamethasone in a rat model of myocardial ischemia-reperfusion." (PMID 40836967, 2024). "Although we have revealed and proved that GXNI can play an anti-acute myocardial ischemia-reperfusion injury via inhibiting the CXCR1-NF-κB-COX-2/ICAM-1/VCAM-1-mediated IL-8 signaling pathway, there are still some issues that need to be addressed by further investigation." (PMID 36325326, 2022). "When myocardial ischemia occurs, vascular endothelial cells are stimulated first; following the activation of NF-κB the expression of a variety of substances, including TNF-α and vascular cell adhesion molecule-1 (VCAM-1), is initiated." (PMID 25667680, 2015). "The activation of NF-κB following myocardial ischemia could induce the production of TNF-α by myocardial tissues in addition to regulating the expression of numerous genes, including IL-1β, IL-6, ICAM-l and VCAM-1." (PMID 25667680, 2015).
periodontal disease (5 papers, 2018 to 2022). "Data suggest that the total amount and concentration of neopterin and VCAM-1 in GCF seemed to be closely associated with periodontal disease severity in CP patients with AMI." (PMID 29641752, 2018). "These correlations in CP patients suggest that CF levels of N and VCAM-1 likely reflect a direct local contribution to the body regarding the severity of periodontal disease." (PMID 29641752, 2018). "Therefore, we might conclude that the severity of periodontal disease influenced the levels of N and VCAM-1." (PMID 29641752, 2018).
peritonitis (5 papers, 2004 to 2023). Inflammation of the peritoneum (tissue that lines the abdominal wall and covers most of the organs in the abdomen). "However, it cannot be excluded that eosinophils rely on other molecules besides VCAM-1, such as MAdCAM-1, to adhere to endothelium in the thioglycolate-induced peritonitis model." (PMID 36756125, 2023). "We hypothesized that MV with high Vt during LPS-induced peritonitis increases coronary VCAM-1 expression, thereby increasing cardiac edema and deteriorating myocardial function." (PMID 22433071, 2012). "In this study we hypothesized that MV with high Vt during LPS-induced peritonitis increases coronary VCAM-1 expression and cardiac edema and thereby aggravates LPS-induced myocardial dysfunction." (PMID 22433071, 2012). "The importance of α4- and α9-integrin/VCAM-1 pathways in neutrophil infiltration in CLP-induced peritonitis remains unclear." (PMID 15274743, 2004). "Vascular/endothelial-specific inflammatory markers indicative of endothelial cell activation were also found elevated after peritonitis, either in short (VEGF), or longer term (soluble VCAM-1; soluble E-selectin)." (PMID 38094743, 2023). "Monitoring of TNF-α-induced expression of the adhesion molecules VCAM-1, ICAM-1 and E-selectin by flow cytometry was used to confirm NF-κB inhibition in endothelial cells, and thioglycollate-induced peritonitis in mice to confirm effects in vivo." (PMID 24329519, 2014). "Plumericin inhibited NF-κB-mediated transactivation of a luciferase reporter gene (IC50 1 μM), abolished TNF-α-induced expression of the adhesion molecules VCAM-1, ICAM-1 and E-selectin in endothelial cells and suppressed thioglycollate-induced peritonitis in mice." (PMID 24329519, 2014).
prediabetes (5 papers, 2018 to 2025). "The remaining 11 proteins were associated only with prediabetes and included vascular cell adhesion protein 1 (VCAM1) and galectin-3-binding protein (LGALS3BP)." (PMID 39589852, 2024). "In the prediabetes group, a significant relationship was found between VCAM‐1 and abstracting (p = 0.011, r = 0.342)." (PMID 39829127, 2025). "For example, VCAM1 declined between 6 and 10 years exclusively in the prediabetes-progressor subpopulation, and this decline matched the downregulation of VCAM1 in the larger group of prediabetes." (PMID 39589852, 2024). "In the prediabetes group, we observed a correlation between VCAM‐1 and abstraction." (PMID 39829127, 2025). "Furthermore, prediabetes-specific proteome features were demonstrated in proteins such as VCAM1 and severity-dependent common proteome with T2D, SHBG, or C3." (PMID 39589852, 2024). "For VCAM‐1, the indirect effect of T2DM on MoCA (X1b) was found to be p = 0.394, with a Sobel test statistic value of 0.851, whereas the indirect effect of prediabetes on MoCA (X2b) was p = 0.818, with a Sobel test statistic value of 0.230." (PMID 39829127, 2025). "VCAM‐1 levels were significantly lower in patients with T2DM compared to both control (p < 0.001) and prediabetes (p = 0.004)." (PMID 39829127, 2025). "In a cohort study that tested the likelihood of developing DM in prediabetic and normoglycemic individuals based on serum VCAM-1 and ICAM-1, individuals with prediabetes were found to have higher concentrations of these indicators than control individuals." (PMID 36983800, 2023). "Moreover, assessment of endothelial function in individuals with prediabetes, using well-established vascular (FMD, EndoPAT) and biochemical (ADMA, VCAM-1, ICAM-1) markers could add context in clinical practice." (PMID 36983800, 2023). "Significant differences in VCAM‐1 and TNF‐α levels were observed; however, these biomarkers did not mediate the effect of T2DM and prediabetes on cognitive functions." (PMID 39829127, 2025).